IL6 (interleukin 6)
Diseases named in the same sentence as IL6 in open-access papers (continued):
Sharing a sentence is not in itself a finding about the gene and the disease.
depression (continued). "For instance, studies of serum IL-6, ICAM-1, and VCAM-1 levels in AD patients and depression patients show some differences." (PMID 38247923, 2024). "IL-10 expression was inhibited in the CUMS model, and increased levels of IL-1β, IL-6, and TNF-α were observed in the sera of the CUMS mice with depression-like behaviors." (PMID 38378622, 2024). "SC therapy can significantly reduce the expression levels of proinflammatory factors such as IL-6, IL-1, and TNF-α in the serum of patients with depression and upregulate anti-inflammatory factors to improve the brain inflammatory response." (PMID 39654612, 2024). "Research has also associated other pro-inflammatory biomarkers with mental health disorders and complement component 3 (C3), interleukin 6 (IL-6), leptin and white blood cell count (WBC) concentrations are reported to be higher in subjects with depression." (PMID 38560580, 2024). "Elevated mRNA and protein levels of interleukin-1β (IL-1β), IL-6, and TNF-α have also been observed in the PFC of patients with depression who died by suicide." (PMID 39484160, 2024). "Pro-inflammatory cytokine levels, such as IL-6 and tumor necrosis factor α (TNF-α), are elevated in the serum and cerebrospinal fluid of patients with depression." (PMID 39484160, 2024). "Pathological studies have observed increased expression of TNF-α, IL, IL-1β, IL-6, and C-X3-C modality chemokine receptor 1 (CX3CR1) in the brain of patients with depression." (PMID 39654612, 2024). "The effectiveness of the treatment was evaluated by the Hamilton Depression Scale (HAMD-17), Self-Depression Scale (SDS), Modified Barthel Index Score (MBI), and the serum levels of IL-1β, IL-6, IL-10, TNF-α, and INF-γ." (PMID 38370556, 2024). "So the administration of asiaticoside to depression-like mice restored the composition of the gut microbiota, could improve intestinal permeability and blood-brain barrier integrity, then could decrease the levels of IL-6, TNF-α, CRH, and CORT and increase hippocampal BDNF levels." (PMID 39494347, 2024). "Elevated levels of inflammatory markers, especially interleukins (IL-6, IL-1α) and tumor necrosis factor-alpha (TNF α), have been identified in patients with major depressive disorder compared to the findings in healthy controls." (PMID 39595067, 2024). "Clinical studies have found that patients with IBS and depression have higher levels of TLR4 expression and IL-6, accompanied by a decrease in IL-10, which indicates that TLR participates in the inflammation reaction in IBS and depression." (PMID 39749341, 2024). "In particular, six studies assessed biomarkers at some time during pregnancy in relation to depression during postpartum, showing a potential predictive role of TNF-a and IL-6 in the diagnosis of PPD." (PMID 38820411, 2024). "Previous studies have shown that the levels of inflammatory markers such as IL-1, IL-6, and TNF-α are significantly elevated in HD patients with depression, suggesting that inflammation plays an important role in the pathogenesis of depression." (PMID 39338552, 2024). "Negative social interactions may increase the levels of pro-inflammatory cytokines, such as IL-6, TNF-α, and positive social support can activate opioid system and produce beta-endorphin that has anti-inflammatory properties, which are associated with depression severity and suicide." (PMID 38459460, 2024). "ROC curve analysis demonstrated that IL-1α, IL-6, and TNF-α showed high accuracy in discriminating patients with severe depression." (PMID 39595067, 2024). "Numerous studies demonstrated alterations in IL-6 and TNF-α levels in patients with depression, bipolar disorder, schizophrenia, and other psychiatric illnesses." (PMID 38339101, 2024). "Meta-analysis has shown that higher concentrations of pro-inflammatory cytokines, such as IL-6 and TNF-α, are observed in subjects with major depression but the results of published studies remain divergent." (PMID 38646609, 2024).
depression (continued). "The results highlighted that IL-6 (AUC = 0.724; 95% CI: 0.648–0.801) and TNF-α (AUC = 0.861; 95% CI: 0.797–0.925) are significant predictors for major depressive disorder." (PMID 39595067, 2024). "Since then, many studies have demonstrated increased levels of acute-phase proteins and pro-inflammatory cytokines such as C-reactive protein (CRP), IL-1, IL-1β, IL-6 and TNF-α in depression." (PMID 38575920, 2024). "Our results are consistent with previous clinical studies, which showed that IL-1β, IL-6, and TNF-α levels were increased in patients with depression." (PMID 39498265, 2024). "The clinical study has reported that elevated levels of pro-inflammatory cytokines IL-1β, IL-6, and TNF-α are observed in depression patients, accompanied by the activation of microglia in the central nervous system." (PMID 38643466, 2024). "Elevated levels of pro-inflammatory cytokines such as interleukin-6 (IL-6), tumor necrosis factor-alpha (TNF-α), and interleukin-1 beta (IL-1β) are commonly observed in individuals with major depressive disorders and suicidal behavior." (PMID 39290301, 2024). "There is evidence that patients with depression have elevated levels of inflammatory cytokines such as tumor necrosis factor alpha (TNF-α), interleukin 1β (IL-1β), and interleukin 6 (IL-6)." (PMID 38983910, 2024). "Numerous studies have shown that inflammatory mediators and cytokines such as interleukin-1β (IL-1β), interleukin-6 (IL-6), and tumor necrosis factor-α (TNF-α) are frequently present in the peripheral blood of patients with depression." (PMID 39114351, 2024). "Acupuncture prevented CUMS-induced depression-like behaviors by reversing the hyper-activation of the HMGB1/TLR4 signaling pathway and by downregulating IL-1β, TNF-α, and IL-6 in the amygdala (AMY) and blood of rats." (PMID 38791125, 2024). "It is evidenced by the vulnerable but significant correlation between the onset and development of depression and elevated levels of inflammatory markers such as CRP, TNF-α, IL-6, and IL-1 (Hacimusalar and Eşel, 2017)." (PMID 38384936, 2024). "A meta-analysis found that levels of IL-6 and TNF are increased in the blood of depression patients." (PMID 39201033, 2024). "For example, researchers have indicated that peripheral blood interleukin-1β (IL-1β), IL-6, tumor necrosis factor-α (TNF-α), and C-reactive protein are the most reliable biomarkers of inflammation in patients with depression." (PMID 38745774, 2024). "In some studies, cytokine inhibitor therapies, such as anti-IL-6 biologics, TNF-α inhibitors, IL-12 and IL-23 antagonists were efficacious in depression." (PMID 38459460, 2024). "Many inflammatory markers, such as IL-6 and TNF-α, exhibited increased levels in the hippocampus and prefrontal cortex (PFC) in major models of depression, such as chronic social defeat stress, chronic restraint stress, and chronic unpredictable mild stress." (PMID 39273621, 2024). "For instance, research has shown that higher PA could reduce interleukin 6 (a kind of inflammatory factor) and produce enough dopamine (a kind of hormone), which may help to improve cognitive function and emotional regulation, thereby reducing symptoms of depression and anxiety." (PMID 39594388, 2024). "Studies report that the plasma levels of proinflammatory cytokines such as interleukin-1β (IL-1β), IL-6, IL-12, CC chemokine Ligand (CCL-2), Tumor Necrosis Factor (TNF)-α, prostaglandin E2 are increased in patients suffering from depression." (PMID 38473935, 2024). "In a Mendelian randomisation study, genetically predicted higher levels of IL-6 were related to increased depressive symptoms, whereas genetic instruments for elevated CRP showed protective effects in depression." (PMID 38699297, 2024).
depression (continued). "Increased IL-6 and TNF-α have been reported in depressive patients and are positively correlated with Hamilton Depression Scale-17." (PMID 38999797, 2024). "For example, the release of cytokines such as IL-12p70, TNF-α, IL-1β, IL-8, IL-6, and interferon-γ (IFN-γ) leads to CSC, including cancer-related fatigue (CRF), sleep disturbances, pain, anxiety, and depression." (PMID 38745774, 2024). "Neutrophils can secrete inflammatory mediators, such as IL-6 and TNF-α, which can damage the brain’s neurotransmitter system and worsen the symptoms of depression." (PMID 39655209, 2024). "Inflammatory cytokines, such as IL-6 and TNF-alpha, are believed to influence brain chemistry and mood regulation, playing a key role in the development of depression." (PMID 39727650, 2024). "A meta-analysis on a total sample of 10,249 individuals revealed that the mean levels of seven inflammatory markers, including IL-6 and TNF-α, were elevated in patients with depression in comparison to healthy controls." (PMID 39273621, 2024). "Based on the IL-6-PGC1α-MFN2 pathway, this study explored the correlation between acute hyper-hypoxia and the occurrence and development of depression, which concluded that acute hyper-hypoxia aggravates the symptoms of depression." (PMID 39135980, 2024). "IL-6 knockout mice and TNF-α receptor knockout mice have shown resistance to the induction of depression." (PMID 38999797, 2024). "High levels of pro-inflammatory cytokines, such as IL-6 and TNF-α, are shared by psoriasis and depression, leading to alterations in serotonin, norepinephrine, and dopamine metabolism in the limbic system and basal ganglia, contributing to depressive symptoms." (PMID 39184643, 2024). "After 24 weeks of HFHSD exposure, male mice showed a general depression in the expression of cytokines, with prominent reduction of TNF-α, IL-6 and IL-13, but increased TGF-β, while female mice showed over-expression of IFN-γ and IL-18." (PMID 39302596, 2024). "Several studies have reported that patients with depression exhibit significantly elevated levels of pro‐inflammatory cytokines, including TNF‐α, IL‐1β, and IL‐6." (PMID 39554370, 2024). "Some pro-inflammatory cytokines such as IL-1, IL-6, and TNF-α, but also corticosteroids and dopamine, play a role in the pathogenesis of depressive disorders in individuals with atopic dermatitis." (PMID 38731996, 2024). "A six-year longitudinal study that looked into the connection between IL-6 and MDD discovered a similar cross-sectional relationship regarding IL-6 levels and an existing depressive disorder." (PMID 39273641, 2024). "GP-14 treatment effectively inhibited the increase of pro-inflammatory cytokines, for example, IL-6, IL-1β, and TNF-α, in the serum from mice in the LPS-induced depression model." (PMID 37631068, 2023). "Further, excessive proinflammatory cytokines release such as MCP-1, IL-1, IL-6, and TNF-alpha leads to behaviors comparable to depression." (PMID 36986674, 2023). "An increase in pro-inflammatory cytokines, namely IL-6, IL-1β, tumor necrosis factor α, and C-reactive protein (CRP), participate actively in the development of depression." (PMID 37139495, 2023). "Previously, it was reported that increased IL-17, IL-6, and TNF-α (the components of the Th17-axis in the current study) contribute to major depressive disorder and chronic fatigue symptoms." (PMID 37509005, 2023). "The antidepressant effect of EGCG was observed in a rat model of chronic unpredictable mild stress-induced depression, where EGCG inhibited neuroinflammation (reduced levels of IL-6 and NO) in the hippocampus." (PMID 36768580, 2023). "Clinical studies found elevated levels of proinflammatory cytokines, such as IL-1β, IL-6, and TNF-α, in patients with major depressive disorder (MDD)." (PMID 37106766, 2023).
depression (continued). "Atractylenolide III can inhibit the increase of pro-inflammatory factors such as IL-1, IL-6, and TNF-α, and alleviate CUMS-induced depression and anxiety-like behavior in rats." (PMID 37694120, 2023). "It is presumed that SIRT1 can inhibit the expression of IL-6 in the CA1 region of the hippocampus, thereby inducing depression." (PMID 37239191, 2023). "IL-6 may increase indoleamine-2,3-dioxygenase (IDO) activity, leading to activation of the kynurenine pathway, which triggers the production of the neurotoxic n-methyl-d-aspartate glutamate agonists quinolinic acid and 3-hydroxykynurenine, causing neurodegeneration and serious depression." (PMID 38084332, 2023). "A meta-analysis of immune markers in the CSF found levels of the cytokines IL-6, IL-8 and TNF-ɑ to be higher in patients with depression as compared to healthy controls." (PMID 37016363, 2023). "The study aimed to investigate the effects of multi-strain probiotic supplementation on serum levels of IL-6, BDNF, nerve growth factor (NGF), and aspects of mental health, including depression, fatigue, and pain." (PMID 38137679, 2023). "A recent study found elevated levels of IL-2, IL-6, and interferon-gamma (IFN-γ) in patients suffering from co-morbid COPD and depression compared to healthy controls, though the implications of these findings remain uncertain." (PMID 37754012, 2023). "Pearson correlations between anxiety-/depression-/cognition deficit-like behaviors and the levels of inflammatory factors (IL-1β, TNF-α, and IL-6) in the hippocampus [r (p)]." (PMID 37560531, 2023). "It is believed that inflammation plays a role in the development of depression, and statins have been shown to reduce the expression of hippocampal pro-inflammatory cytokines such as IL-1β, TNF-α, and IL-6." (PMID 37599890, 2023). "In the rat of CUMS model, rTMS treatment significantly improved anxiety and depression-like behavior and reduced the levels of inflammatory factors TNF-α, iNOS, IL-1β, and IL-6 in the hippocampus." (PMID 36624089, 2023). "Of the proteins assessed, IL-6 and CRP were the only proteins that accounted for a significant indirect effect of adiposity on depression symptoms (IL-6: β = .034, bootstrapped 95% CI [.015.070]; CRP: β = .046, bootstrapped 95% CI [.008.086])." (PMID 37393056, 2023). "Cytokines such as IL-1β, IL-6, TNF-α, and IFN-γ are known for their importance in depression mechanisms." (PMID 37834806, 2023). "Understanding the inflammatory basis of MDD can aid in the identification of specific biomarkers of inflammation such as IL-6 and CRP to provide a more personalized treatment approach and informed therapeutic strategy in patients with Treatment Resistant Depression (TRD)." (PMID 38299049, 2023). "Unipolar depression (Major Depressive Disorder—MDD) has generally been found to stimulate a pro-inflammatory Th1 response (IL-1, IL-2, soluble IL-2 receptor (-sIL-2R), IL-6, C-Reactive Protein (CRP), TNF-α, and IFN-γ), with a subsequent increase in tryptophan catabolites (the kynurenine pathway)." (PMID 37510730, 2023). "And a large number of studies have shown that depressed patients with depression have C-reactive protein (CRP), prostaglandins, and other arachidonic acid derivatives, as well as IL-6, IL-1β and TNF-α were significantly increased." (PMID 37492068, 2023). "Serum level analysis of cortisol, DHEA, TNF-α, IL-6, IL1β in 12 women with BPD and depression (age: 25.6 (3.9)), compared to 12 healthy women (age: 26.3 (5.1))." (PMID 36946840, 2023). "Patients with depression usually have higher concentrations of pro-inflammatory factors such as TNF-α and IL-6 than healthy controls." (PMID 37492068, 2023). "Patients with depression tend to demonstrate significantly elevated levels of various chemokines (CCL2, CXCL10), and pro-inflammatory cytokines, such as interleukin (IL)−1β, IL-6, and tumor necrosis factor (TNF)." (PMID 36978923, 2023).
depression (continued). "In PBMCs of depression patients, TNF-α and IL-6 expression levels were significantly up and downregulated, respectively." (PMID 37575572, 2023). "On the contrary, the elevated serum levels of IL-1β, IL-6, and TNF-α have been repeatedly observed in major depressive disorder and in bipolar disorder." (PMID 33902760, 2023). "The clinical study was based on the outcomes to demonstrate the relationship between TRD and inflammation in human models of depression by measuring inflammatory biomarkers CRP, Interleukin-6 (IL-6) and TNF-α and stress markers (corticosterone)." (PMID 36648973, 2023). "The levels of pro-inflammatory cytokines (such as IL-6, TNF-α) were significantly increased in the serum of patients with depression." (PMID 37305539, 2023). "The clinical samples provided a dose–response relationship, indicating that higher IL-6 and CRP predicted the follow-up progress of depression." (PMID 36846218, 2023). "Inflammatory markers such as interleukin-6 (IL-6) and C-reactive protein (CRP), synthesized by adipocytes, are related to depression-related symptoms." (PMID 37621933, 2023). "Recently, it was discovered that after depression was induced, MCP-1, IL-1, IL-6, and TNF expression increased significantly." (PMID 36986674, 2023). "Again, systemic inflammation (such as in metabolic syndrome) has been suggested to alter the brain DA circuit involved in depression and anhedonia, with the CNS modulation of IFN, IL1, IL6, TNFα, and COX2 levels, as a supposed critical role for TNFα and IL6." (PMID 37511235, 2023). "Some cytokines, such as IL-1β, IL-6 and tumour necrosis factor-α (TNF-α) appear to be involved in the onset and progression of depression." (PMID 37836393, 2023). "In conclusion, exercise can improve depression by inhibiting inflammatory factors (e.g., TNF-α, IL-6, and IL-18) and promoting anti-inflammatory factor TGF-β1, inhibiting the inflammatory response." (PMID 37239191, 2023). "The most pertinent point is that pro-inflammatory cytokines such as IL-6 and TNF impair the expression of BDNF, which leads to the onset of depression." (PMID 36978923, 2023). "At 24 h, elevated IL-2 (p = 0.001) and lower IL-6 (p = 0.035) and IL-17a levels (p = 0.007) ass. with severe PCS at 1 week (p = 0.001).At 6 months, elevated IL-10 ass. with depression (p = 0.004) and PTSD (p = 0.001)." (PMID 37251220, 2023). "The biological link between depression and CVD may be related to the overactivation of the hypothalamic−pituitary−adrenal axis results in the dysregulation of immune system and further causes high levels of proinflammatory cytokines (such as IL‐1β, TNF‐α, and IL‐6) released by macrophages." (PMID 37593998, 2023). "Imbalances between IL-6 and TGF-β and between Th17 and Treg were also found in depressed patients or in animal models of depression, which induces neuroinflammation and neuronal dysfunction." (PMID 37089558, 2023). "The onset of “leaky gut” can trigger an inflammatory response, resulting in symptoms such as lethargy, depression, anorexia, and social withdrawal through the modulation of pro-inflammatory cytokines (TNF-a, IL-6, IL-1B)^142." (PMID 37375546, 2023). "Inflammatory cytokines, such as IL-1β, TNF- α and IL-6 but also HPA axis imbalanced regulation of glucocorticoids, are mainly present in depression and anxiety patients." (PMID 37764111, 2023). "Age-related chronic low-grade inflammation characterized by elevated levels of IL-6 and TNF-α has been reported as an important factor in the occurrence of sarcopenia and the development of depression." (PMID 37920543, 2023). "Elevated levels of inflammatory markers such as IL-1β, IL-6, IL-2, TNF-α, CRP and PGE2 were found in patients with depression." (PMID 37387537, 2023).